CD4 (CD4 molecule)
Diseases named in the same sentence as CD4 in open-access papers (continued):
Sharing a sentence is not in itself a finding about the gene and the disease.
herpes zoster (continued). "The zoster vaccine increases the number of VZV specific CD4+ T cells and older adults have an increase in IFNγ after a second dose of vaccine." (PMID 30537970, 2018). "Here, we assessed transcriptional profiles of whole blood and of isolated activated CD4 T cells and serum concentrations of cytokines in individuals receiving zoster vaccination to build predictive models of T cell responses." (PMID 27764254, 2016). "HIV infection complicated with herpes zoster can decrease CD4+ cells by hindering their maturation, and lead to indirect damages by producing autoimmune response and by inducing the apoptosis of such cells." (PMID 26101481, 2015). "Fourteen patients randomised to early treatment started ART, 13 because of CD4 < 350 cells/mm3, the last patient erroneously because an attack of herpes zoster was considered as stage 3." (PMID 25108448, 2014). "The incidence of herpes zoster seemed to increase for CD4 counts<500 per mm3 but more advanced immunosuppression did not seem to further increase incidence." (PMID 24244647, 2013). "Herpes zoster incidence increased in patients with CD4 counts<500 per mm3 and gradually declined since 1992-1996, with AHR=0.3 (95%CI=0.2-0.5), P<0.001 for the 1997-2002 period and AHR=0.24 (95%CI=0.14-0.4), P<0.001 for the 2002-2008 period." (PMID 24244647, 2013). "In contrast, the cytokine profile seems to differ during infection and vaccination, as vaccine-induced VZV-specific CD4 T-cells showed a multifunctional Th1 phenotype, whereas Th1 CD4 T-cells after acute zoster were functionally restricted and predominantly expressed IFNγ only." (PMID 39265505, 2024). "Based on the observation that the HZ/su vaccine is highly effective, CD4 T-cells may have a dominant role in mediating protection from herpes zoster." (PMID 39265505, 2024). "Finally, five predictors (baseline CD4, age at the initiation of ART, BMI, Herpes zoster and TBIL) were selected as independent risk factors for the INR status." (PMID 37716975, 2023). "Moreover, it is consistent with the reports about the low VZV-specific CD4+ responses from a zoster vaccine." (PMID 38140528, 2023). "Furthermore, it has been shown that the VZV-specific CD4+ T cell response is not only important in limiting the onset of HZ but also frequently adopted as a good indicator for the potential of zoster vaccines." (PMID 38140528, 2023). "Herpes zoster was seen in 12 (5.21%) patients, with a mean CD4 count of 164 cells/mm3." (PMID 37581910, 2023). "Despite the fact that we have not performed any analyses at later time points, we have previously shown that characteristic phenotypical and functional alterations of VZV-specific CD4 T cells in patients with acute herpes zoster reverted back to almost normal values 3 months post VZV-reactivation." (PMID 37880696, 2023). "The relationship between disseminated herpes zoster with CD4 between 200-499 cells/mm3 suggests that, despite having high CD4 counts, severe forms of the disease may occur due to possible T-cell dysfunction and depletion of the immune system." (PMID 35867921, 2022). "Although the untreated control retained normal CD4 levels, it also developed zoster." (PMID 31159224, 2019). "Interestingly, however, the patient who was excluded from the analyses owing to an episode of herpes zoster 1 month before sampling had a markedly higher percentage of VZV-specific CD4 T cells (0.396%) than in the time before zoster (0.010%; data not shown)." (PMID 30413189, 2018). "The adjuvanted recombinant zoster vaccine (RZV) is a novel zoster vaccine containing the VZV gE antigen, a primary target of CD4+ T-cell responses, and a liposome-based AS01B adjuvant." (PMID 39062454, 2024). "Herpes zoster can occur in PLWH at any absolute CD4+ T-cell count, but disease frequency is highest when absolute CD4+ T-cell counts are below 200 cells/μL." (PMID 37766251, 2023).
herpes zoster (continued). "Despite this suppressive effect, it has been shown that VZV specific CD4+ and CD8+ memory T cells did significantly increase after a herpes zoster episode in lung transplant patients." (PMID 35935972, 2022). "In patients #2 and #6, the CD4/CD8 reversal was immediately observed after the onset of herpes simplex encephalitis and herpes zoster, respectively." (PMID 35315593, 2022). "Programmed death receptor (PD-1), a marker of T-cell activation, was also increased in all CD4 and CD8 T-cells during zoster compared to latency, suggesting an antigen-driven response." (PMID 31159224, 2019). "Median CD4 count at HIV diagnosis was similar for cases and controls (535 [IQR 384–666] vs. 523 [IQR 377–690] cells/μL; p = 0.940), but lower for cases at zoster diagnosis (436 [IQR 277–631] vs. 527 [IQR 367–744] cells/μL; p = 0.007)." (PMID 30537970, 2018). "Herpes zoster and its complications are more frequent in patients with attenuated cell-mediated immunity which is mainly maintained by VZV-specific CD4+ T lymphocytes." (PMID 32185277, 2017). "This case shows that cryptococcal meningoencephalitis and herpes zoster can happen together very rarely in an HIV patient with a normal CD4 count." (PMID 40376381, 2025). "Similar CD4+ T and CD8+ T cell responses were induced in mice vaccinated with rChAd63/gE via different immune pathways, which indicated that i.n and i.d injection were also suitable immune routes for a herpes zoster vaccine based on adenovirus." (PMID 38140528, 2023). "We have previously found in immunocompetent individuals and various groups of immunocompromised patients with and without herpes zoster that VZV-specific CD4 T cells show distinct changes in phenotype and functionality in association with herpes zoster." (PMID 30413189, 2018). "This infection occurred in a patient who had a CD4+-T-cell count only slightly above 200/μl before the beginning of therapy, but who had subsequently fallen below 200/μl during therapy and had not received anti-zoster-prophylaxis in between." (PMID 37152008, 2023). "In the unadjusted analysis of the occurrence of herpes zoster, we obtained the hazard ratios 0.43 [0.30, 0.62] (no correction for CD4 cell count), 0.55 [0.38, 0.80] (CD4 cell count as continuous variable), and 0.55 [0.39, 0.80] (CD4 cell count as categorical variable)." (PMID 33284802, 2020). "The incidence of herpes zoster and post-herpetic neuralgia is increased in people living with HIV (PLWH) compared to an age-matched general population, including PLWH on long-term antiretroviral therapy (ART) with no detectable viremia and normal CD4 counts." (PMID 38504173, 2024). "Low CD4 count and lack of ART use appear to be better predictors of future zoster diagnosis." (PMID 30537970, 2018).
lymphedema (55 papers, 2009 to 2026). Excess fluid collection in tissues, causing swelling. "In a mouse tail lymphedema model, CD4-deficient mice have been reported to exhibit significantly reduced lymphedema development compared to wild-type mice." (PMID 39941140, 2025). "The accumulation of fibrotic tissue is tightly connected to the infiltration of CD4+ cells, which are a hallmark of lymphedema and highly present in lymphedematous tissues in our study." (PMID 36421681, 2022). "Attempts to characterize the hallmark inflammatory nature of lymphedema have implicated CD4+ T cells in the inflammatory response leading to lymphedema." (PMID 32268536, 2020). "The role of CD4+ T cells was also studied in a mouse model of secondary lymphedema by use of adoptive transfer techniques in CD4-deficient mice that underwent excision of skin and lymphatics in the tail or dissection of popliteal lymph nodes." (PMID 30761143, 2019). "Research involving human specimens from unilateral upper extremity breast cancer-related lymphedema demonstrated that the number of CD4+ T cells was associated with the severity of lymphedema, and even a small number of these cells were sufficient to induce lymphedema." (PMID 39045461, 2024). "Future studies should analyze the molecular mechanism by which the impaired clearance of dead cells due to the complement deficiency leads to the infiltration of CD4+ T cells and effects of the complement deficiencies on the process of lymphedema through the enhanced inflammation." (PMID 37940849, 2023). "In this study, we characterized participants with filarial lymphedema from Ghana and Tanzania as having low (stage 1–2), intermediate (stage 3–4), or advanced (stage 5–7) lymphedema to determine CD4+ T cell activation patterns and markers associated with immune cell exhaustion." (PMID 37375499, 2023). "Improvements in clinical symptoms of lymphedema after lymphovenous bypass, a procedure in which obstructed lymphatics are shunted to the venous circulation, is associated with decreased tissue fibrosis and decreased CD4+ cell infiltration." (PMID 28186091, 2017). "Importantly, acute damage to lymphatics in mice leads also to aberrant activation of immune cells—in fact, lymphedema-associated AT accumulation appears to be enhanced by CD4+ T cells that secrete mediators promoting growth of dysfunctional and thus leaky lymphatic vessels." (PMID 33854130, 2021). "Additionally, CD4+ T cells have been implicated in the development of secondary lymphoedema." (PMID 33099652, 2020). "CD4+ T cell activation requires an interaction with antigen-bearing dendritic cells, a process that can also occur in lymphedema." (PMID 40821816, 2025). "Our study highlights an oligoclonal expansion of CD4+ T cells in lymphedema and supports insulin as a probable antigen driving T cell responses." (PMID 40821816, 2025). "Together, these prior works underscore the critical role of CD4+ T cells in the chronic inflammatory process of lymphedema." (PMID 40821816, 2025). "During lymphedema, infiltration of immune cells, particularly macrophages and CD4+ T cells, is increased in affected tissues." (PMID 40759794, 2025). "The number of infiltrating CD4+ T cells is significantly correlated with the degree of inflammation and severity of lymphedema, and T helper type 2 (Th2) differentiation is necessary for the histopathological changes observed in lymphedema." (PMID 40821816, 2025). "The study found that CD4+T cells contribute to lymphangiogenesis are activated in regional lymph nodes and migrate to the skin to initiate lymphedema which demonstrates that the CD4+T cell is a potential therapeutic target for the prevention of lymphedema." (PMID 41282012, 2025). "CD4+ cell depletion significantly reduced lymphedema, inflammation, fibrosis, and fat deposition increased lymphangiogenesis, and reduced the pathological changes with lymphedema." (PMID 41282012, 2025).
lymphedema (continued). "Employing biopsy samples from patients with lymphedema, we demonstrated that the CD4+ T cell response is an oligoclonal, antigen-driven expansion." (PMID 40821816, 2025). "Lymphedema and lymphatic stasis also led to CD4+ cell inflammation and mature T helper cell infiltration." (PMID 41282012, 2025). "In lymphedema, the differentiation of naïve CD4+ cells to the Th2 phenotype is important for development of pathology since depletion of these cells prevents development of disease and can be used as a means of treating the disease once it has developed." (PMID 40426856, 2025). "Antigen-activated effector CD4+ T cells were examined in a popliteal lymph node dissection (PLND) model of lymphedema." (PMID 40821816, 2025). "Using high-throughput sequencing, we studied the T cell receptors (TCRs) of CD4+ T cells in paired normal and lymphedema skin biopsies of 11 patients." (PMID 40821816, 2025). "Numerous studies have employed the migration and accumulation of CD4+ T lymphocytes in edematous regions as an innovative therapeutic target for addressing lymphedema." (PMID 41282012, 2025). "In particular, the CD4+ T cell lineage has been shown to comprise most T cells in lymphedema clinical and murine tissues." (PMID 40821816, 2025). "Immunofluorescence staining provided further evidence of significantly higher number of antigen-responsive T cells, as illustrated by the accumulation of activated T cells (CD4+/CD45RO+) in lymphedema skin compared with matched normal skin." (PMID 40821816, 2025). "Since thickening of the dermal and subcutaneous tissues was observed in the early stages of lymphedema, we immunohistochemically observed the infiltration of CD4+ T cells into the lymphedema tissue." (PMID 39941140, 2025). "In the early stage of lymphedema, CD4-positive T cells promote lymphogenesis through macrophage activation." (PMID 39595953, 2024). "The infiltration of the lymphedematous extremities with CD4+T cells influences lymphedema onset and emerges as a promising therapy target." (PMID 39737964, 2024). "The current reduced CD4-positive T cell number suggests the effect of steroid local administration, which is a desirable outcome in managing lymphedema." (PMID 39595953, 2024). "Based on two-way ANOVA followed by the Sidak multiple comparison test, the CD3 + T and the CD4+T cell numbers are statistically significantly higher in patients with lymphoedema." (PMID 38177096, 2024). "In the pathophysiology of lymphedema, the inflammatory response involving CD4+ T cells is the most crucial mechanism, leading to the development of lymphedema." (PMID 39045461, 2024). "Despite the lesser prevalence of CD4+ T-cells in post-operative cutaneous samples, a defining feature of the initial inflammatory response in this form of lymphedema includes infiltration of CD4+ T-cells, CD8+ T-cells, neutrophils, DCs and macrophages." (PMID 38612716, 2024). "To understand the features of the activation state in peripheral CD4+ T cells in lymphedema, we compared the proportions of naive and memory CD4+ T cells among the total CD4+ T cells." (PMID 37250774, 2023). "Elevated CD4+ T cell counts in lymphedematous human tissue samples from affected limbs are correlated with lymphedema stage." (PMID 37886950, 2023). "More CD4+ T cells infiltrated around lymphatic vessels and throughout lymphedema regions of C3 KO mice compared with wild-type mice." (PMID 37940849, 2023). "The number of CD4+ Th cells in the dermis and subcutaneous tissue is positively correlated with the stage of lymphedema." (PMID 37886950, 2023). "We also investigated the infiltration of CD4+ T cells in regions of lymphedema of C5 KO mice; the infiltration of CD4+ T cells into the lymphedema region tended to be increased in C5 KO mice, but without statistical significance." (PMID 37940849, 2023). "In the early stage of lymphedema, CD4+ T cells often activate macrophages to promote excessive lymphangiogenesis, leading to lymphedema." (PMID 37940849, 2023).
lymphedema (continued). "Consistent with previous demonstrations of CD4+ T cells in lymphedema, we noted a marked increase in the presence of CD4+ T cells of the affected hind limb when compared with the control hind limb based on immunohistochemistry." (PMID 38131378, 2023). "Skin and lymph nodes from the region affected of lymphedema appear to have increased levels of macrophage, dendric cells, and particularly, CD4 + cells." (PMID 36571707, 2023). "Specifically, infiltration of Th2 CD4+ T cells characterized by signature cytokines such as IL-4, IL-5, and IL-13 promotes lymphedema but Treg cells inhibit the development of lymphedema." (PMID 37940849, 2023). "Despite the downregulation of PD-1 expression on CD4+ T cells in post-LVA compared with lymphedema, PD-1 expression post-LVA remained significantly higher than the expression in HCs." (PMID 37250774, 2023). "The increased dead cells should trigger the accumulation of CD4+ T cells around lymphatic vessels and throughout lymphedema tissue." (PMID 37940849, 2023). "IFN-γ expression in CD4+PD-1+ T cells was downregulated in post-LVA compared with that in lymphedema (30.1 [19.7–40.9] vs. 24.7 [19.0–26.1], p = 0.04)." (PMID 37250774, 2023). "The expression levels of CD4 in lipohypertrophy were found significantly decreased in comparison to secondary lymphedema as well." (PMID 37108757, 2023). "No prominent augmentation of edematous swelling was observed in C3 KO mouse tails, but there was a significant increase in infiltration of CD4+ T cells in the lymphedema tissues." (PMID 37940849, 2023). "Next, we examined the infiltration of CD4+ T cells, which are known to be critical immune cells involved in the development of lymphedema." (PMID 37940849, 2023). "Although the proportion of Treg I in CD4+ T cells was similar between lymphedema and HCs, it was notable that the proportion of Treg II and Treg III in CD4+ T cells was significantly higher in lymphedema compared to HCs." (PMID 37250774, 2023). "The total proportion of Tregs (including the proportion of Treg I, Treg II, and Treg III) in CD4+ T cells was significantly higher in lymphedema compared to HCs." (PMID 37250774, 2023). "This resulted in reduced lymphedema, suggesting that CD4+T cells impair lymphatic function after lymphatic injury." (PMID 37974224, 2023). "Collectively, these findings illustrate an important and necessary role of CD4+ T cells in the inflammatory response in lymphedema." (PMID 35743063, 2022). "In fact, the inflammatory composition in the rodent lymphedema models is characterized by a predominant CD4+ cell infiltrate, accounting for over 70% of the immune cell load." (PMID 36421681, 2022). "Similar changes have been identified in human specimens collected from patients with unilateral upper extremity breast cancer-related lymphedema, where the number of tissue-infiltrating CD4+ T cells positively correlated with the severity of the disease." (PMID 36421681, 2022). "Several studies focus on the migration and accumulation of CD4+ T cells in the edematous region as a new target to treat lymphedema." (PMID 35886961, 2022). "By contrast, adiposity is normally characterized by a predominance of M1 macrophages, and lymphedema by the infiltration of CD4+ T cells." (PMID 36605202, 2022). "Animal models of lymphedema have also demonstrated that inflammation-induced CD4+ T cells stimulate vascular endothelial growth factor C (VEGF-C) expression." (PMID 35743063, 2022). "Very interestingly, CD4 was significantly more expressed in both specimens from lymphedema patients (C(LE): 1.98-fold, p = 0.011 and LE: 1.66-fold; p = 0.043)." (PMID 36421681, 2022). "These CD4+ T cells produced either IL-4 or IL-13, the two most common anti-inflammatory cytokines, and were key to the severity of lymphedema." (PMID 36386144, 2022).